XRCC4 (X-ray repair cross complementing 4)
Diseases named in the same sentence as XRCC4 in open-access papers (continued):
Sharing a sentence is not in itself a finding about the gene and the disease.
thymic lymphomas (1 paper, 2016). "Cγ1CreXc/+Pc mice (n = 20, green line), which still express XRCC4, developed thymic lymphomas or solid tumors." (PMID 26740101, 2016). "The floxed Xrcc4 allele was deleted in all of the B lineage lymphomas but not in thymic lymphomas and solid tumors (data not shown)." (PMID 26740101, 2016).
Tremor (1 paper, 2025). An unintentional, oscillating to-and-fro muscle movement about a joint axis. "Neurodegenerescence, reported in two adults with XRCC4-related MPD, and suspected in P1 based on progressive pyramidal signs and tremor, is a main feature in Ataxia-Teleangiectasia [MIM#208900], well-reported in Cockayne [MIM#133540, MIM#216400] and Nijmegen syndromes [MIM#251260]." (PMID 40114033, 2025).
tumor predisposition syndromes (1 paper, 2025). "Thus, although these tumors do not appear to be classically associated with any known tumor predisposition syndromes, their rarity, their atypical location and early onset make the hypothesis of a chance association with XRCC4-related MPD unlikely." (PMID 40114033, 2025).
Venous thrombosis (1 paper, 2020). Formation of a blood clot (thrombus) inside a vein, causing the obstruction of blood flow. "Using Biofilter, one interaction nearly met Bonferroni significance: an interaction between rs7735781 in XRCC4 and rs10804247 in XRCC5 was identified for venous thrombosis with a Bonferroni-adjusted likelihood ratio test (LRT) p: 0.0627." (PMID 32915819, 2020).
cancer (46 papers, 2003 to 2026). A tumor composed of atypical neoplastic, often pleomorphic cells that invade other tissues. "Given the potential impact of XRCC4 on tumorigenesis and prognosis, we further analyzed XRCC4 expression in different immune and molecular subtypes of human pan-cancer to investigate the underlying mechanism." (PMID 36765282, 2023). "Then, we further investigated the associations between XRCC4 expression and markers of immune cells in human pan-cancer." (PMID 36765282, 2023). "Meanwhile, we considered genetic alteration, prognostic value of XRCC4, and potential association between the level of expression of XRCC4 and the clinical features and infiltrating immune cells across cancer types." (PMID 36765282, 2023). "Further, genetic variants such as the single nucleotide polymorphism p.Ala247Ser, and other XRCC4 mutations, contribute to cancer susceptibility in non‐BRCA1/2 breast cancer, oral cancer, and hepatocellular carcinoma in humans." (PMID 35000298, 2022). "Surprisingly, a number of LIG4 and XRCC4 polymorphisms have also been identified that associate with a decreased risk of cancer." (PMID 28684677, 2017). "Recently, some studies have reported that the loss of XRCC4 function involves in carcinogenesis of some cancers, and can modify the sensitivity of cancer cells to chemotherapy and radiotherapy." (PMID 29152133, 2017). "Other DNA repair deficiencies may also be reminiscent of XRCC4-related MPD owing to cancer susceptibility, cytopenia, hyper/hypopigmented macules, radial/thumb anomalies, neurodegenerescence and endocrine dysfunction." (PMID 40114033, 2025). "XRCC4 polymorphisms have been identified and subjected to epidemiological studies to assess their potential association with predisposition to various diseases, including cancer." (PMID 38892180, 2024). "Besides, we demonstrated XRCC4 expression characteristic, mutation pattern and function of related-proteins in a variety of human cancers." (PMID 36765282, 2023). "Our findings might be useful for understanding the functions of feline XRCC4 and the associated regulatory mechanisms, and to attain the basic information necessary for developing molecular‐targeted drugs against cancer and MPD." (PMID 35000298, 2022). "The genetic polymorphism at the code 247 of XRCC4 gene (rs3734091) has been reported to be associated with DNA repair capacity and various cancers, indicating that it might play an important role in various cancers." (PMID 24378850, 2013). "Similar to previous reports, XRCC4 expression was significantly different in different immune and molecular subtypes in most cancers, which might suggest that XRCC4 is a potential diagnostic pan-cancer biomarker that involved in immune regulation." (PMID 36765282, 2023). "We examined the effects of global perturbations of O-GlcNAc levels on XRCC4 expression to identify the relationship between elevated cellular O-GlcNAc and XRCC4 protein levels in cancer cells." (PMID 41513635, 2026). "Overall, O-GlcNAcylation of XRCC4 at Thr308 is critical for promoting cancer cell growth and tumorigenesis." (PMID 41513635, 2026). "OGT overexpression in HCT116 cells and other cancer cell lines reversed the decrease in XRCC4 levels under low-glucose conditions." (PMID 41513635, 2026). "This enhances XRCC4 protein stability, increasing its levels and providing resilience to DNA damage in cancer cells." (PMID 41513635, 2026). "To address this, we first investigated the relationship between O-GlcNAcylation, XRCC4 expression, and cancer." (PMID 41513635, 2026). "This approach can be applied using an OGA-fused nanobody that specifically targets XRCC4 to remove O-GlcNAcylation, thereby offering a novel cancer treatment strategy." (PMID 41513635, 2026). "In the present study, we found a positive correlation between XRCC4 expression and cellular O-GlcNAcylation in multiple cancer types, especially in response to DSBs." (PMID 41513635, 2026).
cancer (continued). "According to previous studies, XRCC4 is involved in cell cycle control, which critically affects cancer progression." (PMID 41513635, 2026). "We found that bleomycin-induced DNA damage upregulated cellular O-GlcNAc and XRCC4 levels in various cancer cell types." (PMID 41513635, 2026). "Previous studies have shown that XRCC4 participates in cell cycle regulation and functions as a pivotal tumor suppressor that plays a central role in controlling cancer progression." (PMID 41513635, 2026). "Third, the correlations between XRCC4 expression and prognosis of human cancers and immune cell infiltration lack direct evidence." (PMID 36765282, 2023). "We observed that XRCC4 overexpression was associated with poor OS, DFS or RFS in 11 types of cancers." (PMID 36765282, 2023). "This comprehensive pan-cancer analysis study elaborated statistical correlations between XRCC4 expression and clinical prognosis, molecular and immune subtypes, immune cell infiltration, immune-related genes and drug sensitivity." (PMID 36765282, 2023). "The correlations between XRCC4 expression and molecular and immune subtypes of human cancers were explored by TISIDB database." (PMID 36765282, 2023). "XRCC4 expression was related to the radiotherapy response of cancer patients, but little was researched in the field of drug sensitivity or resistance till now." (PMID 36765282, 2023). "Considering the specific role of XRCC4 in cancers, we conducted the systemic analysis to explore the potential role of XRCC4 across cancer types." (PMID 36765282, 2023). "The findings provide new evidence for the potential role of XRCC4 exerted during tumorigenesis process in human cancer." (PMID 36765282, 2023). "The XRCC4 expression was related to the molecular and immune subtypes of human cancers, and the survival outcome of 11 types of cancers, including KIRC, STAD and LIHC." (PMID 36765282, 2023). "Transcriptomic dataset available via TCGA and GTEx to explore expression profile of XRCC4 across cancer types and normal tissues." (PMID 36765282, 2023). "Due to the abnormal expression of XRCC4 across cancers, we explore the genetic alteration of XRCC4 in human cancers." (PMID 36765282, 2023). "The findings presented above suggest that XRCC4 plays a role in the prognosis and immunity of cancers." (PMID 36765282, 2023). "Mechanistically, RIG-I hinders the formation of the XRCC4/LIG4/XLF complex on DSB by interacting with XRCC4, thereby disrupting DNA repair and rendering cancer cells sensitive to radiation therapy." (PMID 37679817, 2023). "As immune cell infiltration in the TME was strongly correlated with the effects of the immunotherapy, we further analyzed the correlation between XRCC4 expression and immune cell infiltration in human pan-cancer." (PMID 36765282, 2023). "Although XRCC4 was overexpressed in most cancer types, the result of survival prognosis analysis for the XRCC4 indicated different results for different tumors." (PMID 36765282, 2023). "We found that XRCC4 expression was strongly associated with marker genes of Th1 cells, DC, TAM, M2 macrophage, monocyte, regulatory T cells (Tregs) and Th2 cells across cancer types." (PMID 36765282, 2023). "In this work, we found XRCC4 expression was significant correlated with TILs, significant and nonsignificant correlations were found in different cells and cancer types." (PMID 36765282, 2023). "XRCC4 silencing increases the radiosensitivity of various cancer cells in humans, including breast, colon, and lung cancers." (PMID 35000298, 2022). "Then, we analyzed the correlation between lncSBF2-AS1 and XRCC4 expression in 20 recurrent GBM cancer tissues." (PMID 30992025, 2019). "Previous studies have provided sufficient evidence that XRCC4 decrease plays a radiosensitization effect in various human cancers." (PMID 30842344, 2019).
cancer (continued). "Functionally, XRCC4 overexpression increased while XRCC4 knockdown reduced the IC50 of cancer cells to doxorubicin." (PMID 29152133, 2017). "TUNEL assay further proved that the overexpression of XRCC4 significantly decreased the death of cancer cells." (PMID 29152133, 2017). "The immunohistochemistry staining exhibited that a minority of XRCC4 proteins were expressed in the nucleus of cancer cells, and most were localized at their cytoplasm." (PMID 29152133, 2017). "In this analysis, cancer cells were first transfected with the vector expressing XRCC4 or its null vector, and next treated using a series of concentrations of anti-drug (0.01 to 40 μM)." (PMID 29152133, 2017). "Particularly, XRCC4 can predict therapeutic value of TACE treatment through modifying the tumor cells’ sensitivity to anti-cancer drugs used in this treatment procedure." (PMID 29152133, 2017). "Taken together, our findings suggest that some vicarious mechanisms, only partly relying on the activation of the A-NHEJ pathway, make the XRCC4 protein remarkably dispensable in humans, at least to warrant immunologic proficiency and anti-cancer surveillance." (PMID 25872942, 2015). "XRCC2 and XRCC4 showed higher expression in tumor tissues and cells with respect to non cancer tissues/cells." (PMID 24616890, 2014). "We did not observe any abnormalities in expression level or migration pattern of the following NHEJ proteins in radiosensitive cancer cases: Ku70, Ku80, XRCC4, DNA Ligase IV." (PMID 12698192, 2003). "We carried out and report here the results of Western blot analysis testing for abnormalities of DNA ligase IV, XRCC4, Ku70 and Ku80 in a cohort of severely radiosensitive cancer patients." (PMID 12698192, 2003). "We confirmed the correlation between intracellular O-GlcNAc and XRCC4 levels in cancer cells." (PMID 41513635, 2026). "Given that XRCC4 WT exhibits greater variability in O-GlcNAcylation levels than XRCC4 T308A, these results indicate that XRCC4 O-GlcNAcylation mediates the relationship between global O-GlcNAc levels and cancer cell growth." (PMID 41513635, 2026). "However, the precise regulatory mechanism linking O-GlcNAcylation to XRCC4 function in cancer cells remains to be determined." (PMID 41513635, 2026). "Additionally, we explored cancer therapy strategies through DNA damage repair by modifying the O-GlcNAcylation of XRCC4 at Thr308." (PMID 41513635, 2026). "XRCC4 and global O-GlcNAcylation levels were concurrently elevated in various cancer cell types." (PMID 41513635, 2026). "We wanted to probe whether XRCC4 O-GlcNAcylation mediated the relationship between global O-GlcNAcylation levels and cancer cell growth." (PMID 41513635, 2026). "Therefore, we investigated how O-GlcNAcylation of XRCC4 affects cancer cell responses to DNA DSBs induced by bleomycin, a radiomimetic and chemotherapeutic drug commonly used in DNA repair studies and a DNA damage-inducing agent." (PMID 41513635, 2026). "Increased XRCC4 levels enabled the cancer cells to resist the stress of DNA damage." (PMID 41513635, 2026). "We propose that targeting the O-GlcNAcylation of XRCC4 at Thr308 could be a promising strategy for cancer therapy." (PMID 41513635, 2026). "Furthermore, using the DNA damage marker γH2AX, we observed that DNA repair was less efficient in XRCC4 T308A-expressing cells compared to XRCC4 WT-expressing cells, resulting in increased cancer cell death." (PMID 41513635, 2026). "Additionally, experimental studies indicate that the knockdown of XRCC4 or epigenetic inhibition of LIG4/XRCC4/XLF complex formation increases cancer cell sensitivity to anticancer agents." (PMID 41513635, 2026). "Furthermore, different stress factors trigger the DDR or genomic instability, increasing the expression of DDR-related proteins such as XRCC4 and promoting cancer progression." (PMID 41513635, 2026). "Cancer cell resilience to DNA damage from therapy may rely on XRCC4, stabilized by O-GlcNAcylation at Thr308." (PMID 41513635, 2026).
cancer (continued). "Additionally, XRCC4 Thr308 O-GlcNAcylation promotes cancer proliferation, invasion, and in vivo tumor growth." (PMID 41513635, 2026). "CCK-8 assay of XRCC4-depleted cancer cells overexpressing XRCC4 WT or XRCC4 Y66F mutant in multiple cisplatin concentrations (0, 2.5, 5, 10 μM) over 72 h further confirm that lactate-mediated NHEJ activation through XRCC4–LIG4 complex assembly is a key mechanism underlying chemoresistance." (PMID 41462961, 2025). "To test whether the LTR10.XRCC4 enhancer regulates XRCC4 function in cancer, we subjected control and knockout cells to 10-Gy irradiation and found that knockout cells showed reduced viability following irradiation." (PMID 39018396, 2024). "Although these results should be validated by additional researches, they indicated that XRCC4 may play a role in the prognosis and immunotherapy response in cancers and is a promising therapy target." (PMID 36765282, 2023). "Strong correlations were also found between XRCC4 and immune checkpoint genes in 33 human cancers." (PMID 36765282, 2023). "The findings provide mechanistic evidence supporting the hypothesis that XRCC4 plays a vital role in the formation, treatment response and survival prognosis across cancer types." (PMID 36765282, 2023). "XRCC4 was expressed at intermediate level in malignant cells among the datasets, and XRCC4 expression level was quite different in distinct cell types, which might be the source of cancer microenvironment heterogeneity." (PMID 36765282, 2023). "However, the mechanisms of molecular biology and clinical implications of XRCC4 in cancers are still unclear and need to be further elucidated." (PMID 36765282, 2023). "The results indicated that XRCC4 expression level may influence the response to the targeted molecular therapy drugs, and XRCC4 has potential to be a novel target for cancer therapeutics in the future." (PMID 36765282, 2023). "The result of comparison of XRCC4 expression of the pan-cancer with normal tissues in the XIANTAO Academic showed that XRCC4 mRNA expression was significantly high among most cancer types except KICH and PRAD, which was consistent with the TIMER database results." (PMID 36765282, 2023). "This study aimed to systematically investigate the role of XRCC4 across cancer types." (PMID 36765282, 2023). "It was found that XRCC4 is significantly overexpressed in most of the human cancers and negative associated with the prognosis." (PMID 36765282, 2023). "This comprehensive pan-cancer analysis suggested that XRCC4 may play a vital role in the prognosis and immunotherapy response in cancer patients, and it is a promising therapy target in the future." (PMID 36765282, 2023). "This and further studies might be useful to elucidate the role of NHEJ in feline radio‐resistance and the role of abnormal XRCC4 in diseases, including cancers and MPD, and to develop XRCC4‐targeted drugs, such as radiosensitizer, for humans and cats." (PMID 35000298, 2022). "Indeed, targeting NHEJ at the level of XRCC4 interactions represents an attractive approach to sensitise cancer cells, commonly displaying cryptic DNA repair pathway defects including NHEJ, via synthetic lethality and/or other mechanisms." (PMID 35420136, 2022). "In the context of radiation therapy, active XRCC4 could reduce DSB-mediated apoptotic effect on cancer cells." (PMID 33184404, 2020). "Although rs3734091 has been identified as a cancer-causing variant, it should be noted that the homozygous A247S variant does not fully abolish XRCC4 function." (PMID 25360583, 2014). "Additionally, XRCC4 expression is also upregulated in cancer cells." (PMID 41513635, 2026). "Thus, reducing XRCC4’s O-GlcNAcylation level alongside conventional therapy may enhance cancer cell sensitivity to treatment." (PMID 41513635, 2026).